ENSG00000276304
Gene: Miscellaneous RNA gene on chromosome 3 (139,233,414 to 139,233,520, forward strand). Ensembl gene ENSG00000276304.
Homologues: Orthologues: mouse Gm55625 (87% identical). Paralogues in human: PISRT1 (99% identical).